INS (insulin)
Diseases named in the same sentence as INS in open-access papers (continued):
Sharing a sentence is not in itself a finding about the gene and the disease.
steatosis (continued). "LCN2 is a downstream TNF inflammatory molecule associated with hepatic steatosis and insulin insensitivity." (PMID 31892368, 2019). "CAP evaluation showed steatosis in 36.3% of baseline patients (8/22), associated with higher BMI, waist circumference, insulin, and alanine aminotransferase (ALT) levels." (PMID 31275240, 2019). "Nevertheless, under insulin resistant status, the hepatic lipogenesis-promoting activity of IL-4 renders the liver more susceptible to develop steatosis by increasing FFA uptake and endogenous lipid synthesis." (PMID 30584465, 2018). "HCV infection causes oxidative stress leading to impairment of insulin action, steatosis, fibrosis, apoptosis, gene expression alteration, and HCC." (PMID 30366460, 2018). "A deeper look into the liver microarray data revealed a number of genes implicated in steatosis and insulin sensitivity that were differentially regulated by intermittent metformin treatment." (PMID 29167747, 2017). "Together, the data suggest that reduced inflammation in AO underlies the improved insulin sensitivity and lowered steatosis compared to YO." (PMID 27033445, 2016). "The increase of lipids in the generation of steatosis tends to be associated with progressive metabolic deregulation, particularly hepatic insulin alteration and the development of inflammation." (PMID 25324698, 2014). "In patients with chronic HBV, the insulin sensitizing adipokine adiponectin, and its receptor AdipoR2were associated with steatosis." (PMID 23914225, 2013). "In conclusion, in patients with chronic HBV, the insulin sensitizing adipokine adiponectin, and its receptor AdipoR2 were associated with steatosis." (PMID 23914225, 2013). "From a pathogenic perspective, hepatic insulin resistance, the metabolic milieu of steatosis, is associated with biliary cholesterol secretion, a mechanism to explain cholesterol gallstone formation." (PMID 22848440, 2012). "Collectively, based on the fact that HBV, especially HBx proteins, induces hepatic steatosis and inflammation, we examined the possible association with HBx and insulin signaling." (PMID 20351777, 2010). "Increased levels of circulating fatty acids caused by insulin resistance and increased adipocyte lipolysis can accumulate within the liver resulting in steatosis." (PMID 17472743, 2007). "These proteins have been proven to be associated with fibrosis but also with steatosis, steato-hepatitis and insulin resistance pathways." (PMID 17096854, 2006). "All of these pathways are supported by our previous evidence showing molecular perturbations to these pathways, and the physiological consequences including reduced fatty acid oxidation, deficient insulin signalling, liver inflammation and steatosis in Pcyt2 + /- mice." (PMID 40153413, 2025). "Treatment with a synbiotic containing the LP B21060 strain showed reduced inflammation and steatosis in the liver tissue in a rat model of feeding with a diet enriched in fat associated with reduced impairment of insulin signaling and preserved gut barrier integrity." (PMID 40284576, 2025). "In addition, olivetol significantly improved the histological appearance of the liver and pancreas, preventing the development of steatosis and the loss of insulin secretion by beta cells." (PMID 39857767, 2025). "This suggests an increased activity of the TCA cycle when steatosis is present, speculated to function as a progenitor of increased gluconeogenesis, a hallmark of the insulin-resistant steatotic liver." (PMID 37591342, 2023). "Presence of focal steatosis was associated with higher requirements of exogenous insulin." (PMID 37711891, 2023). "Additionally, macrophage accumulation in omental, not subcutaneous, adipose tissue is associated with aggravated steatosis and fibro-inflammation in insulin-resistant obese subjects independently of altered glycemic status." (PMID 35747386, 2022).
steatosis (continued). "Moreover, ectopic deposition of lipids in hepatocytes during NAFLD (steatosis) directly or indirectly inhibits key parts of the insulin signaling pathway and significantly increases the risk of T2DM." (PMID 36684872, 2022). "Indeed, we found a significant association between steatosis and fasting insulin, even with insulin plasma levels within normal range." (PMID 35892670, 2022). "In general, a weight loss of 3–5% improves insulin sensitivity and steatosis." (PMID 36612019, 2022). "Because OSI-906 also blunts insulin signaling as well as insulin deficiency, liraglutide may have a protective effect on steatosis in the OSI-906-treated model." (PMID 33105604, 2020). "In addition, patients with hepatic IR and CHC infection are associated with steatosis and higher expressions of intrahepatic inflammatory cytokines and reactive oxygen species, which can potentially interfere with insulin signaling." (PMID 31540136, 2019). "Mitochondrial dysfunction is a potential cause of hepatic insulin resistance and steatosis." (PMID 29602237, 2018). "Moreover, methionine and choline deficient diet-induced steatosis can lead to liver cancer in rodents, but such diet improves insulin sensitivity." (PMID 28496104, 2017). "Together, these processes limited the expansion of this fat pad and as a consequence, lipid flux shifted towards the liver, causing steatosis and hepatomegaly, which may contribute to the marked insulin resistance." (PMID 29028831, 2017). "However, independent of the groups, weight loss of greater than 5% led to improved insulin sensitivity and steatosis, while those that lost 9% or more of body weight had greater histological improvement." (PMID 27006654, 2016). "Therefore, loss of insulin sensitivity in addition to excessive calorie intake is predicted to be required for more than early stage steatosis to arise." (PMID 27632189, 2016). "Mechanism of steatosis in GADD34-deficient mice may be mainly comes from the effect of GADD34 on insulin signaling because eIF2α phosphorylation in GADD34-deficient mice was not significantly increased by HFD and aging." (PMID 26316333, 2015). "The liver injury could have been caused by steatosis, a disease state characterized by inflammation, fibrosis, cell death and insulin resistance." (PMID 24119309, 2013). "Dysfunction of insulin causes damage to the pathway of carbohydrates and fats, which provides the basis for the flow of fatty acids to the liver, increases the synthesis and storage of triglycerides, and finally increases the levels of inflammation and steatosis in the body." (PMID 38755622, 2024). "This could include evaluation of the role of many (often functionally unconfirmed) GWAS-associated NAFLD risk variants in the context of steatosis and under different culture conditions—for example, by evaluation of different carbohydrate sources and concentrations as well as insulin levels." (PMID 36823355, 2023). "Indeed, despite developing a steatosis associated with hepatic IR, these mice are characterized by improved skeletal muscle insulin sensitivity and glucose tolerance, as well as a drastic reduction in white AT depots and the appearance of brown-like adipocytes in this tissue." (PMID 35409319, 2022). "Therefore, although IL-4 exhibits positive regulatory effects to boost insulin efficacy, the energy deposit-promoting activity of IL-4 may make the liver more susceptible to develop steatosis under insulin resistant and diabetic models." (PMID 30584465, 2018). "In this regard, it is plausible that adequate magnesium intake, which is related to improved insulin senstivity and inflammation, may slow development and progression of steatohepatitis and steatosis and in turn reduce the risk of mortality due to liver disease." (PMID 29263344, 2017).
steatosis (continued). "It established a high-fat diet (HFD)-induced NAFLD rat model and evaluated the therapeutic effects of different dosage groups, including liver injury, oxidative stress, glucose metabolism, steatosis, and insulin homeostasis (via fasting glucose tolerance)." (PMID 41683224, 2026). "In HFD–fed mice, systemic administration of SHLP2 via intraperitoneal (IP) injection improved glucose tolerance and insulin signaling, reduced hepatic lipogenic gene expression and steatosis, increased energy expenditure, and suppressed food intake." (PMID 41543486, 2026). "One included study showed the association between deranged liver parameters and NODM incidence, possibly due to liver inflammation and steatosis promoting peripheral insulin resistance." (PMID 41378064, 2025). "In the liver, a lack of curcumin results in increased SREBP1c-driven lipogenesis and suppressed β-oxidation via PPARα activation, along with aggravated NF-κB/TGF-β signaling and reduced insulin sensitivity, leading to steatosis and fibrosis." (PMID 41471280, 2025). "Dysregulation of hepatic lipid metabolism, a hallmark of MASH, increases ceramide accumulation, promoting lipotoxicity, insulin resistance, steatosis, and eventually HCC." (PMID 40057751, 2025). "There was a moderate but significant correlation between steatosis score and liver TG content (Spearman rho = 0.461, p = 0.05), and liver TG content correlated positively with insulin levels (Pearson r = 0.458, p = 0.04)." (PMID 40476757, 2025). "Upon stratification, the correlation among the case group for fibrosis score with daily insulin dosing remained significant while steatosis correlated at a p value of 0.052." (PMID 40568565, 2025). "This lipotoxicity impairs insulin signaling, thereby inducing oxidative stress and leading to intrahepatic steatosis." (PMID 40474897, 2025). "Orotate, and cinnamate correlated negatively and significantly with BMI, steatosis and 24h insulin dosage." (PMID 40568565, 2025). "A meta-analysis of RCTs investigating the impact of probiotics on MASLD revealed that probiotics exerted a beneficial regulatory effect on liver function, steatosis, blood glucose levels, insulin levels, and blood lipid levels." (PMID 40871398, 2025). "The aromatic amino acid, tyrosine was in the top correlating compounds for BMI and insulin dosage while phenylalanine was predictive of steatosis." (PMID 40568565, 2025). "Several compounds elevated in our case cohort and were among the top metabolites correlated with steatosis, BMI, and insulin dosing." (PMID 40568565, 2025). "Glutamate, pyruvate, alanine, valine, lactate, and CAR 5.0 correlated positively and significantly with BMI, steatosis, and 24h insulin dosage with variable results for other compounds." (PMID 40568565, 2025). "Methylmalonate correlated positively with BMI and 24h insulin dosage and had a near significant positive correlation with steatosis (p=0.051)." (PMID 40568565, 2025). "Hepatic Lepr overexpression effectively ameliorated both the steatosis and reduced insulin sensitivity induced by the IAL‐miRs upregulation." (PMID 39792613, 2025). "Proline correlated positively with BMI and steatosis and had a near significant positive correlation with 24h insulin dosage (p=0.058)." (PMID 40568565, 2025). "Wy-14643 is a powerful PPARα agonist that can inhibit steatosis, restore insulin sensitivity, as well as lipid and adiponectin levels, thereby reducing MASLD caused by PPARα dysregulation." (PMID 41377566, 2025). "The expected benefit of RES + HESP treatment of MASLD is correction of hepatic insulin resistance, steatosis, and inflammation." (PMID 41196673, 2025). "These inherited anti‐Lepr miRNAs, also referred to inherited anti‐Lepr miRNAs (IAL‐miRs), modulate hepatic steatosis, and insulin signaling through the Lepr regulatory Igfbp2, Egfr, and Ampk." (PMID 39792613, 2025). "Curcumin is extracted from Curcuma Longa, has insulin-sensitizing effects and reduces liver inflammation and steatosis." (PMID 40142198, 2025).
steatosis (continued). "This intricate network not only directly facilitates the progression of hepatocyte steatosis, inflammatory injury, and fibrosis but also acts as a crucial link connecting systemic insulin resistance to liver-specific pathological alterations." (PMID 41377803, 2025). "Transfer of free fatty acids to the liver is due to high blood glucose levels and low insulin production, which in turn leads to steatosis and vice versa." (PMID 40951584, 2025). "It enhances insulin sensitivity, reduces liver injury and steatosis, and inhibits key hepatic enzymes and transcription factors such as G6Pase, FBP-1, and SREBP1, which are crucial in gluconeogenesis and lipogenesis." (PMID 40689212, 2025). "Liver disease: CIA is the model with more evidence, replicating pathologies like steatosis, fibrosis, and insulin resistance when coupled with dietary challenges (e.g., high-fat diets)." (PMID 41267875, 2025). "Viral proteins interfere with hepatic insulin signalling, promote steatosis, and sustain systemic inflammation, all of which contribute to impaired glucose regulation." (PMID 41583303, 2025). "Sensitivity analysis revealed that the correlation of steatosis with insulin dosing among the case group became significant at a p value of 0.025." (PMID 40568565, 2025). "The study revealed for the first time that PLEO exerts a hepatoprotective effect by regulating lipid metabolism, inhibiting inflammatory responses, and increasing insulin sensitivity to alleviate FFA-induced steatosis in HepG2 cells." (PMID 41199858, 2025). "Our previous studies examining paternal alcohol exposures reveal that both fetal and adolescent offspring exhibit early indicators of MASLD, including increased hepatic fibrosis, steatosis, and alterations in insulin sensitivity." (PMID 39908263, 2025). "We confirmed TRPV1 expression in the liver and demonstrated that CAP activates hepatic TRPV1, thereby preventing steatosis, improving insulin sensitivity, reducing inflammation, and enhancing fatty acid oxidation." (PMID 40864772, 2025). "A reduction from baseline steatosis by week 12 was documented for 55.0% of the patients receiving oral insulin compared to 1.2% in the placebo arm." (PMID 39131144, 2024). "Murine changes were most prominent in the liver, where we observed inhibition of insulin and estrogen receptor signaling with concomitant hepatic insulin resistance and steatosis." (PMID 38862620, 2024). "In contrast, the treatment of HFD-fed male C57BL6/J mice with KPA for 6 weeks improved insulin sensitivity and glucose tolerance and ameliorated steatosis." (PMID 39404414, 2024). "Our study suggests that GLP-1R agonists improve insulin sensitivity, glycaemic control, steatosis, and pancreatic beta cell function in CGL and, likely, in lipodystrophies more broadly." (PMID 38745956, 2024). "Patients receiving insulin showed a median −1.1 kPa and −21.0 dB/m reduction from baseline fibrosis and steatosis levels, respectively, while placebo-treated patients showed median increases of 0.3 kPa and 13.0 dB/m, respectively." (PMID 39131144, 2024). "Through a variety of mechanisms, including steatosis promotion, insulin signaling disruption, fibrotic protein synthesis by stellate cells, and neutrophil recruitment, IL-1β contributes to the pathogenesis of non-alcoholic steatosis." (PMID 39179677, 2024). "It has been shown to affect skeletal muscle mass by regulating epithelial cell function and protein synthesis pathways, increasing ATP production, promoting fat oxidation, and limiting muscle steatosis, reducing insulin sensitivity, and improving inflammation." (PMID 39006102, 2024). "The results revealed a significant improvement in liver enzymes (ALT and GGT) and steatosis after 12 weeks among patients on exenatide over insulin (p-value < 0.001 and p < 0.01, respectively)." (PMID 39063598, 2024).
steatosis (continued). "When mice were given CMPF before or after being fed a high-fat diet, it enhanced overall lipid metabolism, improved insulin sensitivity, increased beta-oxidation, lowered lipogenic gene expression, and mitigated steatosis." (PMID 38921446, 2024). "Palmitoleic acid inhibits steatosis in the liver and improves insulin sensitivity by modulating GLUT-4 and AMPK phosphorylation." (PMID 38435365, 2024). "They demonstrated typical features such as inflammation, necrosis, steatosis, fibrosis, and dysregulated insulin signaling in steatosis." (PMID 39594577, 2024). "This study utilized healthy human PCLSs to simulate MASLD onset, showing that GFIPO—rich in sugars, insulin, and fatty acids—induces macrovesicular steatosis, inflammation, and ECM accumulation compared to controls." (PMID 38474754, 2024). "Patients receiving insulin showed a median −1.2 kPa and −21.0 dB/m reduction from baseline fibrosis and steatosis levels, respectively, while placebo-treated patients showed median increases of 0.3 kPa and 13.0 dB/m, respectively." (PMID 39131144, 2024). "After oxidation of bilirubin to biliverdin in the mitochondria, biliverdin must be exported to the cytoplasmic lysate for reduced bilirubin, and studies have found enhanced redox of bilirubin increases insulin resistance and steatosis in obese patients." (PMID 37056283, 2023). "Conspicuously, the glycogen storage in the subcapsular part of the liver was depleted together with the fat droplets, which we interpreted as a sign of hepatic insulin resistance despite its recovery from steatosis." (PMID 37929025, 2023). "Biochemical results showed that HFHCCC induced elevated hepatic lipids, blood glucose, insulin; marked hepatocyte steatosis, ballooning, inflammation, and fibrosis." (PMID 37244987, 2023). "Steatosis as quantified by an increase of triglycerides after 48 h in culture, is induced by incremental supplementation of sugars (glucose and fructose), insulin, and fatty acids (palmitate, oleate)." (PMID 37208356, 2023). "It has effects on increased insulin sensitivity and anti-steatosis by inhibiting insulin secretion and suppressing hepatic glucose production and lipogenesis in the initial stage of the disease." (PMID 37180779, 2023). "Numerous studies have reported the beneficial effects of the ACE2/Ang1-7/MAS axis in counteracting steatosis and non-alcoholic inflammation, liver fibrosis, and insulin sensitivity in the liver." (PMID 36901403, 2023). "Both enzymes are also critical for steatosis development in insulin-resistant states, and inhibitors of ACC and FASN are currently in clinical development for NASH." (PMID 37937648, 2023). "Rnf13 knockout in hepatocytes exacerbate insulin resistance, steatosis, inflammation, cell injury and fibrosis in the liver of diet-induced mice, which can be alleviated by Rnf13 overexpression." (PMID 37857628, 2023). "The resulting changes in circulating blood insulin/glucose levels can affect (hepatic) lipid metabolism and lead to lipid accumulation in hepatocytes (steatosis)." (PMID 37168981, 2023). "In mice lacking fatty acid transporter protein 5 (Fatp5), improvement of steatosis and systemic insulin sensitivity was evident." (PMID 37998747, 2023). "Compared to CAF, CAFQ lowered plasma glucose, increased liver IRS‐1 mRNA expressions, increased pancreatic β‐cell insulin immunoreactivity, and lowered hepatocyte degeneration and microvesicular steatosis." (PMID 37970433, 2023). "Sleeve gastrectomy reduced pancreas steatosis and inflammation and improved insulin sensitivity and synthesis." (PMID 37274331, 2023). "The vicious cycle resulting from hepatocyte steatosis, insulin resistance, the inflammatory response, and liver fibrosis was aggravated by TRIM38 deficiency in hepatocytes." (PMID 37116711, 2023). "Liver steatosis induces higher rates of gluconeogenesis, and muscle tissue steatosis reduces insulin-mediated glucose uptake." (PMID 38260129, 2023).